TNF (tumor necrosis factor)
Diseases named in the same sentence as TNF in open-access papers (continued):
Sharing a sentence is not in itself a finding about the gene and the disease.
rheumatoid arthritis (continued). "In rheumatoid arthritis (RA), Tregs recover their suppressive function after immunomodulating treatment with anti-tumor necrosis factor (TNF) α monoclonal antibody (Ab) therapy." (PMID 29774027, 2018). "The objective of the study was to evaluate a plausible role of polymorphisms within the NKG2D gene as a predictor of how effective anti-tumor necrosis factor (TNF) therapy is in rheumatoid arthritis (RA) patients." (PMID 29370129, 2018). "However, an abnormal persistent release of TNF-α could result in autoimmune diseases, such as rheumatoid arthritis (RA), psoriasis, and others." (PMID 29743640, 2018). "Tumor necrosis factor is a major pro-inflammatory cytokine which triggers various physiological consequences by binding to and trimerizing its receptors, and has been the single most sought-after drug target for intervening autoimmune diseases such as rheumatoid arthritis and psoriasis." (PMID 29743640, 2018). "In another example, tumor necrosis factor-α (TNF-α) is a pro-inflammatory cytokine over-expressed in the joints of rheumatoid arthritis (RA) patients." (PMID 30469350, 2018). "Persistently elevated levels of TNF are evident in chronic inflammatory disorders, e.g., rheumatoid arthritis (RA), inflammatory bowel disease (IBD), ankylosing spondylitis (AS) and psoriasis." (PMID 29751683, 2018). "The role of TNF-α in the control of bacilli in the latent stage has also been demonstrated by the reactivation of tuberculous infection (including miliary and extrapulmonary) in patients with Crohn’s disease and rheumatoid arthritis, after treatment with monoclonal anti-TNF-α antibodies." (PMID 29515555, 2018). "A following more detailed study, including patients with active rheumatoid arthritis and high insulin resistance, confirmed these findings while it also proved restoration of mediators' phosphorylation in the insulin signaling cascade, after 12 weeks of treatment with anti-TNF agents." (PMID 29576769, 2018). "About 14 years ago, we have identified that along the course of rheumatoid arthritis (RA), the immune system produces neutralizing autoantibodies against tumor necrosis factor alpha (TNFα), one of key drivers of the inflammatory process in this disease." (PMID 29651292, 2018). "TNF inhibitors may lead to a relative enrichment of M2 Mφ by inhibiting M1 Mφ function, because we have previously shown that HO-1 mRNA expression in circulating monocytes is increased during treatment with infliximab in patients with rheumatoid arthritis." (PMID 29895319, 2018). "Indeed, it was observed that infection of Toxoplasma gondii is associated with neuronal impairment and inflammation in mice and humans and the inhibition of TNF signaling in patients suffering from rheumatoid arthritis is protective against Alzheimer's disease." (PMID 30214903, 2018). "Registry studies provide a valuable source of comparative safety data for tumor necrosis factor inhibitors (TNFi) used in rheumatoid arthritis (RA), but they are subject to channeling bias." (PMID 29329557, 2018). "Studies have shown that, compared with nonbiologic disease-modifying antirheumatic drugs, TNF-α-blocking agents may contribute to the reduction of the risk of cardiovascular events in patients with rheumatoid arthritis." (PMID 29348768, 2017). "Interestingly, interleukin-1β (IL-1β) and tumor necrosis factor-α (TNF-α), which increase under pathological conditions, such as rheumatoid arthritis (RA) and osteoporosis, induce the expression of RANKL in osteoblasts and stromal cells, eventually enhancing osteoclast formation." (PMID 29104576, 2017). "Two hundred eight rheumatoid arthritis (RA) and psoriatic arthritis (PsA) patients have been evaluated longitudinally for at least 1-year before and 2-years after anti-TNF-α therapy introduction for the possible appearance of a lymphocyte expansion." (PMID 28222785, 2017). "Tumor necrosis factor inhibitors (TNFi) are common second-line treatments for rheumatoid arthritis (RA)." (PMID 28506320, 2017).
rheumatoid arthritis (continued). "In rheumatoid arthritis (RA) and spondyloarthritis, two frequent and severe diseases, TNF-α mediates a wide variety of effector functions, including the production of pro-inflammatory cytokines and chemokines, activation of immune cells and angiogenesis." (PMID 29184553, 2017). "Tumor necrosis factor (TNF) is detrimental in several chronic inflammatory diseases such as rheumatoid arthritis (RA), inflammatory bowel disease (IBD) and psoriasis." (PMID 29057962, 2017). "Reduction in inflammation can decrease arterial stiffness, which was demonstrated among others in patients with rheumatoid arthritis (RA) undergoing therapy with anti-tumor necrosis factor-α (TNF-α) agents." (PMID 28912780, 2017). "Biologic TNFα inhibitors are a mainstay treatment option for patients with rheumatoid arthritis (RA) refractory to other treatment options." (PMID 28488248, 2017). "For example, in rheumatoid arthritis (RA) patients, the disease process is successfully intervened in by anti-TNFα agents that interrupt the inflammatory responses." (PMID 28286780, 2017). "The cytokine tumor necrosis factor alpha (TNFα) promotes inflammatory diseases, such as rheumatoid arthritis (RA) and Crohn’s disease." (PMID 28349965, 2017). "Indeed, many assume that the systemic form is mainly driven by IL-1 responsible for fever or increased serum inflammatory marker, while the articular pattern is more similar to rheumatoid arthritis and may be principally driven by TNF-α." (PMID 28659802, 2017). "The aim of this study was to compare the TNF-α levels in saliva among patients with Rheumatoid arthritis (RA) and chronic periodontitis as well as healthy subjects." (PMID 28061876, 2017). "TNF-α blockers present a revolutionizing therapeutic choice for inflammatory diseases such as RA, AS, plaque psoriasis, psoriatic arthritis, juvenile polyarticular rheumatoid arthritis, and inflammatory bowel disease (CD and ulcerative colitis)." (PMID 28337644, 2017). "Therapeutic agents that target the inflammatory cytokines IL-1β and TNF-α have been successful in treating rheumatoid arthritis (RA) and related diseases." (PMID 29284451, 2017). "In anti-TNF treated rheumatoid arthritis (RA) patients, we measured the expression of these biosignatures in blood, and in skin biopsies from the site of tuberculin skin tests (TSTs) as a human experimental model of multivariate cell-mediated immune responses." (PMID 28824652, 2017). "Cytokines such as tumour necrosis factor (TNF)-α, interleukin (IL)-1 and IL-6 play a fundamental role in the pathogenesis of rheumatoid arthritis (RA)." (PMID 27913894, 2017). "It binds to TNFα and decreases its role in disorders involving excess inflammation in ankylosing spondylitis, adolescent rheumatoid arthritis, psoriasis, psoriatic arthritis, and rheumatoid arthritis and, potentially, in a variety of other disorders mediated by excess TNFα." (PMID 28044081, 2016). "In this regard, TNF-α has been found to play not only a pivotal role in the pathogenesis of atherosclerosis but also in many other chronic inflammatory diseases, e.g. asthma, chronic obstructive pulmonary disease, rheumatoid arthritis and inflammatory bowel disease." (PMID 27467817, 2016). "Etanercept is a recombinant fusion protein approved for the treatment of TNF-α mediated diseases such as rheumatoid arthritis (RA), psoriasis, psoriatic arthritis, and ankylosing spondylitis." (PMID 27382576, 2016). "TPD significantly attenuated TACE-mediated disease models of sepsis, rheumatoid arthritis (RA) and inflammatory bowel disease (IBD), and reduced TNFα in synovial fluids from RA patients." (PMID 27982031, 2016). "The aim of this study was to evaluate the involvement of TNF-α and insulin resistance (IR) in the inflammatory process, oxidative stress, and disease activity in patients with rheumatoid arthritis (RA)." (PMID 27340510, 2016).
rheumatoid arthritis (continued). "Although AS patients tend to have fewer conventional tuberculosis-related comorbidities than rheumatoid arthritis (RA) patients, the growing use of TNF inhibitors to treat AS has raised incidences of tuberculosis to a level similar to that in RA patients." (PMID 27101309, 2016). "CD27+ memory B cells have a greater capacity to produce TNFα than naive B cells in patients with rheumatoid arthritis (RA)." (PMID 27044386, 2016). "Patient TN2 was undergoing treatment with soluble tumor necrosis factor-alpha (TNF-α)/lymphotoxin-alpha (LT-α) receptor for therapy of rheumatoid arthritis with Sjögren syndrome at the time of collection; IFI27 expression could be indirectly induced by this treatment." (PMID 27100186, 2016). "Tumor necrosis factor alpha (TNFα) plays a key role in the pathogenesis of rheumatoid arthritis (RA)." (PMID 26977076, 2016). "In this study, we assessed whether clinical and ultrasonography (US)-based remission could be used to select patients with rheumatoid arthritis (RA) eligible to taper and discontinue anti-TNF-α therapy after achievement of remission, looking at disease relapse." (PMID 26842890, 2016). "In addition, serum MIP-1α levels has been reported to be higher in AS patients than those in rheumatoid arthritis (RA) patients and healthy controls, and anti-TNFα therapy appeared to reduce serum MIP-1α levels though with lower efficacy in AS than in RA patients." (PMID 27698377, 2016). "We did a systematic review of studies comparing discontinuation of tumor necrosis factor alpha (TNF) antagonists in rheumatoid arthritis (RA) patients, pooled hazard ratios and assessed clinical and methodological heterogeneity." (PMID 27930739, 2016). "Recent studies on rheumatoid arthritis (RA) demonstrate that discontinuation of biologic agents, including anti-TNF-α agents, could be feasible for maintaining low disease activity without any additional therapies, suggesting potential of providing clinical benefits for patients with RA." (PMID 27034879, 2016). "Rheumatoid arthritis (RA) and Crohn’s disease (CD) are autoimmune disorders with a crosstalk between their pathogenesis such as increased expression of TNF in the target organs." (PMID 27731365, 2016). "Like other pro-inflammatory cytokines such as TNFα and IL-1β, IL-6 is an important therapeutic target of immune disorders, and anti-IL-6 receptor antibody, tocilizumab, has been developed as a therapy in human diseases, including rheumatoid arthritis (RA) and Castleman’s disease." (PMID 27070121, 2016). "A previous study determined that RA (rheumatoid arthritis) patients treated with infliximab for 6 weeks produced anti-infliximab antibodies to inhibit binding of the drug to TNFα." (PMID 27578555, 2016). "Currently, adalimumab (otherwise known as Humira) is the representative TNF-α blocker for the treatment of rheumatoid arthritis (RA) and other common inflammatory arthropathies." (PMID 27652157, 2016). "Tumor necrosis factor α (TNF-α) plays a central role in the occurrence and progression of rheumatoid arthritis (RA)." (PMID 27594856, 2016). "The increased expression of ADAMTS-7 in the joint tissues of degenerative diseases, such as OA and rheumatoid arthritis (RA), patients is due to proinflammatory cytokines, including TNF-α." (PMID 25653475, 2015). "A host of proinflammatory cytokines, namely, tumor necrosis factor (TNF-α), IL-1β, and IL-6, are involved in the pathogenesis of rheumatoid arthritis (RA) and are crucial to determine progression of chronic joint inflammation and concomitant bone erosion." (PMID 25784780, 2015). "TCZ was approved in Europe in 2009 for the treatment of moderate to severe rheumatoid arthritis (RA) in patients with an inadequate response to one or more disease-modifying antirheumatic drugs (DMARDs) and/or tumor necrosis factor (TNF) antagonists." (PMID 25830224, 2015).
rheumatoid arthritis (continued). "Description: The goal of this challenge was to use a crowd-based competition framework to develop a validated molecular predictor of anti-TNF response in Rheumatoid Arthritis (RA)." (PMID 27134723, 2015). "In the Spanish BIOBADASER registry, among 4,706 patients with chronic arthritis, including rheumatoid arthritis (RA), psoriatic arthritis (PsA), and AS, 488 had been treated with more than one TNF-α inhibitor over a 4-year period." (PMID 26176701, 2015). "For example, bone resorption can be upregulated due to cytokines such as TNFα and IL-6 in systemic inflammatory diseases such as rheumatoid arthritis (RA)." (PMID 26041376, 2015). "Certolizumab pegol, a PEGylated tumour necrosis factor (TNF)-inhibitor, improves the clinical signs and symptoms of rheumatoid arthritis (RA) when used in combination with methotrexate or as monotherapy." (PMID 26124700, 2015). "We have hypothesized that incompatibility between the G1m genotype of the patient and the G1m1 and G1m17 allotypes carried by infliximab (INX) and adalimumab (ADM) could decrease the efficacy of these anti-tumor necrosis factor (anti-TNF) antibodies in the treatment of rheumatoid arthritis (RA)." (PMID 25885039, 2015). "The objective of this study was to directly compare the safety of tocilizumab (TCZ) and TNF inhibitors (TNFIs) in rheumatoid arthritis (RA) patients in clinical practice." (PMID 25880658, 2015). "In the remainder of the studies, the most frequently reported treatment for rheumatoid arthritis included disease-modifying antirheumatic drugs (methotrexate, sulfasalazine, and leflunomide), biologic therapy (anti-TNF-α), corticosteroids (prednisolone), and/or nonsteroidal anti-inflammatory drugs." (PMID 26347200, 2015). "Sometimes a hunch has been right, for example, the initial organ transplants with chemical immunosuppression already discussed, and the highly successful use of anti-tumour necrosis factor (TNF)α monoclonals to treat refractory rheumatoid arthritis (RA)." (PMID 25750245, 2015). "The advent of anti-tumor necrosis factor alpha (anti-TNFα) drugs has considerably improved medical management in rheumatoid arthritis (RA) patients, although it has been reported to be ineffective in a fraction of them." (PMID 25860297, 2015). "The introduction of Tumor Necrosis Factor (TNF) inhibitors has revolutionized the treatment of rheumatoid arthritis (RA)." (PMID 25848939, 2015). "The central role of TNF in inflammatory disorders has been demonstrated by the ability of agents that block the action of TNF to treat a range of inflammatory conditions, including rheumatoid arthritis, ankylosing spondylitis, inflammatory bowel disease and psoriasis." (PMID 26618095, 2015). "For example, mAbs based on research of TNFα were developed to treat rheumatoid arthritis (RA) for patients presenting with medium and severe symptoms." (PMID 25811022, 2015). "To date, most of the safety information regarding anti-TNF therapy has come from rheumatoid arthritis (RA)." (PMID 26559487, 2015). "The clinical efficacy of specific cytokine inhibitors in rheumatoid arthritis (RA) reveals the pivotal role of predominantly monocytic cytokines like IL-1β, TNF or IL-6 in the pathogenesis of the disease." (PMID 26251236, 2015). "Thus, the case report of a patient with an initial diagnosis of rheumatoid arthritis who developed pericarditis caused by WD (diagnosed by pericardial biopsy) and the patient who had not been treated previously with TNF-α blocker." (PMID 26215452, 2015). "Interestingly, there is increasing evidence that TNF antagonists may improve insulin resistance in patients with psoriasis and rheumatoid arthritis." (PMID 26633680, 2015). "In recent years the treatment of rheumatoid arthritis (RA) has been transformed by the development of biologics targeting tumour necrosis factor alpha (TNFα)." (PMID 25344414, 2014).
rheumatoid arthritis (continued). "A 71-year-old Caucasian male was diagnosed with symptomatic acute Q fever (based on positive C. burnetii PCR followed by seroconversion) while using anti-tumor necrosis factor-α (anti-TNFα) drugs for rheumatoid arthritis (RA)." (PMID 24931640, 2014). "The management of rheumatoid arthritis (RA) is primarily based on the use of disease-modifying antirheumatic drugs (DMARDs), mainly comprising synthetic chemical compounds (that is, methotrexate or leflunomide) and biological agents (tumor necrosis factor inhibitors or abatacept)." (PMID 25608624, 2014). "About the subject “the role of tumor necrosis factor in ischemic reperfusion injury", Koenig and colleagues in 2006 have done the study and showed that pentoxifylline significantly reduces the production of tumor necrosis factor in rheumatoid arthritis patients." (PMID 24734070, 2014). "Since 1999, anti-TNF-α therapy has been used with success in the treatment of patients suffering from rheumatoid arthritis (RA), inflammatory enterocolitis (Crohn's disease and ulcerative colitis), spondyloarthropathies, or psoriasis." (PMID 24719524, 2014). "Proinflammatory signaling that is activated by TNF-α is an important aspect in the pathology of rheumatic autoimmune diseases such as ankylosing spondylitis (AS) and rheumatoid arthritis (RA)." (PMID 24783218, 2014). "The concurrence of reduced numbers of circulating progenitor cells and elevated plasma levels of VEGF and TNF-α have also been reported in other conditions where systemic inflammation may contribute to vascular impairment, as in rheumatoid arthritis or congestive heart failure." (PMID 25171153, 2014). "The immune inflammatory disorders rheumatoid arthritis (RA), psoriatic arthritis (PsA) and psoriasis (Ps) share common pathologic features and show responsiveness to anti-tumor necrosis factor (TNF) agents yet they are phenotypically distinct." (PMID 25333715, 2014). "In the present study, the transcriptional regulation in synovial fibroblasts (SFBs) isolated from rheumatoid arthritis (RA) patients was studied by modeling the response to 4 external stimuli (IL-1 β, TNF- α, TGF- β, and PDGF-D)." (PMID 24989895, 2014). "Aberrant TNFα signaling leads to the development of pathological conditions including cardiovascular disease, and therapeutic blocking of TNFα signaling has been proposed for the treatment of several inflammatory diseases particularly rheumatoid arthritis and bowel disease." (PMID 24804145, 2014). "TNF α inhibitors are now widely used for treatment of aggressive rheumatoid arthritis (RA) and other rheumatic diseases." (PMID 24949211, 2014). "Serum TNF-α level in patients with various inflammatory diseases such as rheumatoid arthritis, ankylosing spondylitis or TNF receptor-associated periodic syndrome was known to be increased after treatment with soluble receptor or anti-TNF antibody irrespective of efficacy." (PMID 24939012, 2014). "MYD88 has been found to be involved in IBD pathology and the involvement of MYD88 in response to TNF-blocking drugs has been demonstrated in studies on rheumatoid arthritis (RA) patients." (PMID 25015298, 2014). "For example, rheumatoid arthritis, a chronic autoimmune disease characterized by joint destruction, is considered to be driven by the secretion of pro-inflammatory cytokines including TNFα and IL-17 from lymphocytes, resulting in excessive activation of osteoclasts." (PMID 25490771, 2014). "Antitumor necrosis factor-alpha (TNF-α) agents are widely used for effective treatment of autoimmune rheumatic and dermatological diseases such as rheumatoid arthritis (RA), ankylosing spondylitis (SA), psoriasis (Ps), or psoriatic arthritis (PsA)." (PMID 25114684, 2014). "Anti–tumor necrosis factor (anti-TNF) therapies are highly effective in rheumatoid arthritis (RA) and psoriatic arthritis (PsA), but a significant number of patients exhibit only a partial or no therapeutic response." (PMID 23460124, 2013).